MAF1 (MAF1 negative regulator of RNA polymerase III)
Description:
Plays a role in the repression of RNA polymerase III-mediated transcription in response to changing nutritional, environmental and cellular stress conditions to balance the production of highly abundant tRNAs, 5S rRNA, and other small non-coding RNAs with cell growth and maintenance. Also plays a key role in cell fate determination by promoting mesorderm induction and adipocyte differentiation (By similarity). Mechanistically, associates with the RNA polymerase III clamp and thereby impairs its recruitment to the complex made of the promoter DNA, TBP and the initiation factor TFIIIB. When nutrients are available and mTOR kinase is active, MAF1 is hyperphosphorylated and RNA polymerase III is engaged in transcription. Stress-induced MAF1 dephosphorylation results in nuclear localization, increased targeting of gene-bound RNA polymerase III and a decrease in the transcriptional readout. Additionally, may also regulate RNA polymerase I and RNA polymerase II-dependent transcription through its ability to regulate expression of the central initiation factor TBP.
Synonyms: DKFZp586G1123
Tractability: Antibody: its Gene Ontology location is reachable by antibodies, with medium confidence. PROTAC: UniProt records ubiquitination sites on it; ubiquitination databases record sites on it.
Gene: Protein-coding gene on chromosome 8 (144,103,112 to 144,107,618, forward strand). Ensembl gene ENSG00000179632.
Subcellular location: Nucleus; Cytoplasm
Subcellular location (Human Protein Atlas): Nucleoplasm; Cytosol
Pathways (Reactome):
Signal Transduction: Regulation of PTEN gene transcription
Gene Ontology:
Molecular function: protein binding; RNA polymerase III type 1 promoter sequence-specific DNA binding; RNA polymerase III type 2 promoter sequence-specific DNA binding; RNA polymerase III type 3 promoter sequence-specific DNA binding; RNA polymerase III core binding; GABA receptor binding
Biological process: negative regulation of transcription by RNA polymerase I; negative regulation of transcription by RNA polymerase III
Cellular component: cytoplasm; cytosol; nucleoplasm; nucleus; axon; dendrite; inhibitory synapse; perinuclear region of cytoplasm; plasma membrane
Genetic constraint (gnomAD): Loss-of-function variants: 7 observed, 29.74 expected, observed/expected ratio (o/e) 0.24, 90% interval 0.13 to 0.44. The upper end of that interval is the gene's LOEUF score, 0.44, which puts it in group 1 of 6, group 1 being the genes least tolerant of losing a copy. Missense variants: 214 observed, 306.1 expected, observed/expected ratio (o/e) 0.7, 90% interval 0.62 to 0.78. Synonymous variants: 139 observed, 110.73 expected, observed/expected ratio (o/e) 1.26, 90% interval 1.09 to 1.45.
Homologues: Orthologues: chimpanzee MAF1 (100% identical), guinea pig MAF1 (97% identical), macaque MAF1 (97% identical), dog MAF1 (96% identical), rat Maf1 (95% identical), mouse Maf1 (95% identical), pig MAF1 (81% identical), tropical clawed frog maf1 (73% identical), zebrafish maf1b (71% identical), Drosophila melanogaster Maf1 (49% identical), Caenorhabditis elegans mafr-1 (29% identical).
Diseases named in the same sentence as MAF1 in open-access papers:
MAF1 is named in the same sentence as 43 diseases in open-access papers, as found by Europe PMC text mining. Sharing a sentence is not in itself a finding about the gene and the disease. The quoted sentences say what the papers report.
breast carcinoma (7 papers, 2015 to 2025). "Decreased MAF1 expression is associated with increased breast cancer stage." (PMID 37801436, 2023). "Taken together, we sought to determine if MAF1 could also be implicated in HER2+ breast cancer." (PMID 37801436, 2023). "We wanted to determine if the observed MAF1 amplifications correlated with mRNA and protein expression changes in breast cancer datasets." (PMID 37801436, 2023). "Using the cBioPortal, we queried the proteogenomic landscape of breast cancer dataset to determine if MAF1 expression was altered in breast cancer." (PMID 37801436, 2023). "In HER2-positive breast cancer patients, MAF1 expression significantly increases and correlates with five years of relapse-free survival in response to trastuzumab treatment, suggesting MAF1 is a predictive biomarker in breast cancer." (PMID 37801436, 2023). "The monarcHER trial results prompted a preliminary investigation of MAF1 regulation by the CDK4/6 inhibitor abemaciclib in HER2-positive breast cancer." (PMID 37801436, 2023). "This study aims to determine if MAF1 expression correlates with clinical outcomes in HER2-positive breast cancer." (PMID 37801436, 2023). "We report that MAF1 is amplified in 39% of all breast cancer sub-types, and the observed amplification co-occurs with MYC." (PMID 37801436, 2023). "In this study, we analyzed clinical breast cancer datasets to determine if MAF1 alterations correlate with clinical outcomes in HER2-positive breast cancer." (PMID 37801436, 2023). "Herein, we report that MAF1 is amplified in 39% of all breast cancer sub-types, and the observed amplification co-occurs with MYC." (PMID 37801436, 2023). "Our Kegg pathway analysis provides details for MAF1 involvement in a variety of human cancers, including breast cancers, S3 Fig." (PMID 37801436, 2023). "The current study is the first to correlate MAF1 alterations with clinical outcomes in HER2-positive breast cancer." (PMID 37801436, 2023). "We utilized the University of Alabama at Birmingham Cancer data analysis portal (UALCAN) and queried the TCGA breast cancer dataset to correlate MAF1 amplification with changes to MAF1 mRNA expression." (PMID 37801436, 2023). "Protein-protein interaction analysis, S2A Fig, indicates MAF1 interacts with known proteins deregulated in breast cancer." (PMID 37801436, 2023). "This study aims to determine if MAF1 expression is altered in breast cancer subclasses and if MAF1 alterations correlate with clinical outcomes in breast cancer sub-types." (PMID 37801436, 2023). "Further analysis shows that novel therapies in clinical trials for HER2 therapy-resistant breast cancers regulate MAF1 expression." (PMID 37801436, 2023). "Using various bioinformatics tools, we screened breast cancer datasets for alterations in MAF1 expression." (PMID 37801436, 2023). "Recently, MAF1 expression has been demonstrated to be altered in colorectal and liver carcinomas and Luminal B breast cancers." (PMID 37801436, 2023). "Trastuzumab-treated HER2-positive breast cancer patients demonstrated an increased five-year relapse-free survival with significantly increased MAF1 expression." (PMID 37801436, 2023). "We then used the ROC Plotter platform with a dataset of drug-treated cell lines to determine if MAF1 is regulated by novel therapies newly developed to treat HER2-positive breast cancer." (PMID 37801436, 2023). "Searching the TCGA dataset using the UALCAN platform identified MAF1 (p = 0.03) as a prognostic marker in breast cancer." (PMID 37801436, 2023). "More extensive studies are warranted to determine if MAF1 serves as a predictive and prognostic biomarker in breast cancer." (PMID 37801436, 2023). "In the current experimental study, we scrutinized the chemoprotective effect of astraxanthin against the 7,12-dimethylbenz(a)anthracene (DMBA)-induced breast cancer via Nrf-2-Keap1 and NF-kB and mTOR/Maf-1/PTEN pathway." (PMID 31556759, 2019).
breast carcinoma (continued). "Lastly, we also report increased MAF1 expression correlating with an increased five year relapse-free survival response to trastuzumab treatment, suggesting MAF1 is a predictive biomarker in breast cancer." (PMID 37801436, 2023). "Hence, we analyzed MAF1 expression in response to anti-HER2 therapies in breast cancer cell lines and patients." (PMID 37801436, 2023). "MAF1 expression decreased in subclasses of breast cancer, including HER2-positive breast cancer." (PMID 37801436, 2023). "Together, data suggest MAF1 may serve as a predictive biomarker and a novel target for drug design for patients with breast cancer resistant to anti-HER2 therapies." (PMID 37801436, 2023). "Thus, using the CPTAC and ICPC datasets available in UALCAN, which contains larger sample sizes from more diverse populations, we sought to determine if MAF1 expression is altered in breast cancer patients by ethnicity and age." (PMID 37801436, 2023). "Our data suggest that MAF1 may be a novel target for therapeutic development for patients with HER2-positive breast cancer." (PMID 37801436, 2023). "In a sample size of 192 luminal B breast cancer patients, MAF1 copy number is amplified." (PMID 37801436, 2023). "Furthermore, patients treated with trastuzumab had a significant increase in MAF1 expression (p = 0.0012) in the five-year relapse-free survival dataset (p = 2.7 x 10−6, AUC = 0.874), suggesting MAF1 can potentially be a predictive biomarker in HER2-positive breast cancer." (PMID 37801436, 2023). "MAF1 protein expression is significantly decreased in luminal, HER2-positive, and TNBC breast cancer subtypes and MAF1 mRNA expression is increased substantially in breast cancer cell lines treated with anti-HER2 therapies." (PMID 37801436, 2023). "In SKBR3 and BT474 breast cancer cell lines treated with anti-HER2 therapies, MAF1 mRNA expression is significantly increased." (PMID 37801436, 2023). "MAF1 mRNA expression is significantly increased in SKBR3 and BT474 breast cancer cell lines treated with anti-HER2 therapies." (PMID 37801436, 2023). "Based on the results that anti-HER2 therapies increase MAF1 and TFIIIB expression in HER2-breast cancer cell lines, we then queried breast cancer patients treated with anti-HER2 therapies using ROC Plotter." (PMID 37801436, 2023). "We examined HER2, MAF1, and MYC expression in the five-year relapse-free breast cancer patient dataset, restricting our query to HER2-positive samples (n = 564)." (PMID 37801436, 2023). "Four genes WWTR1, RIN1, MAF1 and SHARPIN were identified having significant expression levels in breast cancer patients by meta-analysis." (PMID 27792127, 2016). "MAF1 amplification correlated with increased methylation of the MAF1 promoter and MAF1 protein expression is significantly decreased in luminal, HER2-positive, and TNBC breast cancer subtypes." (PMID 37801436, 2023). "We speculate that targeting MAF1 activity in HER2-breast cancer and HER2-positive breast cancer patients who have developed resistance to standard therapies will be of clinical value in assessing novel therapies." (PMID 37801436, 2023). "In stage 2 and 3 breast cancer, MAF1 protein expression is significantly reduced compared to normal and protein expression is significantly decreased in all breast cancer patients, independent of race and age." (PMID 37801436, 2023). "MAF1 protein expression is also significantly reduced in stage 2 and 3 breast cancer compared to normal and significantly decreased in all breast cancer patients, regardless of race and age." (PMID 37801436, 2023). "The decrease of MAF1 RNA and protein expression in breast cancer, including HER2-positive breast cancer, prompted us to investigate whether anti-HER2 therapies regulate MAF1 expression." (PMID 37801436, 2023). "MAF1 and MYC protein expression decreased in HER2-positive breast cancer." (PMID 37801436, 2023).
breast carcinoma (continued). "Furthermore, we constructed a breast cancer in situ transplantation model using MDA-MB-453 (EGFP marker) to verify the Role of CHI3L1/MAF in promoting TNBC stemness and participating in immunosuppression by exogenously administering hrCHI3L1 or/and sh-MAF-1." (PMID 37838657, 2023). "SHARPIN was involved in prostate cancer and breast cancer progression but its role in breast cancer metastasis was still unknown, while MAF1 had no known involvement in cancer progression." (PMID 27792127, 2016). "MAF1 is a negative regulator of TFIIIB-mediated RNA polymerase III transcription and has not been well characterized in breast cancer." (PMID 37801436, 2023).
Obesity (6 papers, 2015 to 2025). Accumulation of substantial excess body fat. "We conclude that whole body loss of MAF1 results in mice that are lean and profoundly resistant to diet-induced obesity and fatty liver disease." (PMID 25934505, 2015). "Note, however, that the effect on obesity demonstrated in mice may also be observed in Drosophila with a more severe loss of Maf1 function, e.g., resulting from a gene deletion." (PMID 40663502, 2025). "In mice, null mutation of Maf1 confers resistance to diet-induced obesity." (PMID 40663502, 2025). "Maf1-/- mice are shorter than WT mice and exhibit a lean phenotype with resistance to diet-induced obesity, decreased fertility and fecundity, and increased longevity/healthspan." (PMID 35611941, 2022). "The importance of MAF1 for metabolic economy reveals the potential for MAF1 modulators to protect against obesity and its harmful consequences." (PMID 25934505, 2015). "Overall, we found that the function of Maf1 in aging was conserved in flies and could be uncoupled from an effect on obesity." (PMID 40663502, 2025). "The function of MAF1 as a chronic repressor of pol III transcription in mammalian systems helps to rationalize the obesity resistant phenotype of Maf1−/− mice, which is due in part to the wasteful use of metabolic energy and is driven, we propose, by a futile RNA cycle." (PMID 32686713, 2020). "The obesity and fatty liver disease resistance of the whole-body Maf1 knockout may have, in part, a basis in metabolic inefficiency similar to that of the liver-specific knockout of NML." (PMID 25934505, 2015). "Thus, Maf1−/− mice are resistant to obesity as a result of both reduced caloric intake (feeding) and increased energy expenditure." (PMID 25934505, 2015). "How the different molecular effects of the Maf1 knockout are partitioned in terms of energy expenditure and obesity resistance has yet to be determined, but our current results already establish MAF1 as a novel and unconventional therapeutic target for the treatment of obesity and related diseases." (PMID 25934505, 2015). "However, a role for Gm35339 in obesity resistance is unlikely since two MAF1-null lines bearing different indels created by a targeted zinc finger nuclease do not have elevated levels of Gm35339 transcripts yet resist weight gain on a high fat diet like Maf1−/− mice." (PMID 32686713, 2020). "Here we show that a whole-body knockout of Maf1 in mice confers resistance to diet-induced obesity and nonalcoholic fatty liver disease by reducing food intake and increasing metabolic inefficiency." (PMID 25934505, 2015).
glioblastoma (4 papers, 2014 to 2025). The most malignant astrocytic tumor (WHO grade IV). "Consistent with this concept, expression of Maf1 in PTEN-deficient human glioblastoma cells inhibits anchorage-independent growth." (PMID 25502566, 2014). "Furthermore, expression of Maf1 in PTEN-deficient human glioblastoma cells inhibits anchorage-independent growth." (PMID 32732865, 2020). "Previous studies of Maf1 knockdown and overexpression in glioblastoma cells found inverse changes in the expression of the TATA-box-binding protein (TBP) at the RNA and the protein level that correlated with changes in RNA Pol I transcription." (PMID 25934505, 2015). "Compared to adjacent tissues, we found that Maf1 mRNA was upregulated in cholangiocarcinoma (CHOL), liver hepatocellular carcinoma (LIHC), and glioblastoma multiforme (GBM)." (PMID 41339318, 2025).
hepatoma (4 papers, 2014 to 2025). "Similarly, lowered MAF1 levels were associated with increased lipid accumulation in mouse hepatoma cells, and increased insulin-like signaling in D. melanogaster." (PMID 38143800, 2023). "Increased expression of Fasn and Acc1 mRNAs was also seen in mouse hepatoma cells following MAF1 knockdown and was attributed to decreased direct recruitment of MAF1 to the corresponding promoters." (PMID 38143800, 2023). "Three matched normal tissues and hepatocellular carcinomas that were PTEN negative were examined by immunostaining for potential changes in Maf1 expression." (PMID 25502566, 2014).
Sepsis (4 papers, 2020 to 2025). Sepsis is defined as life-threatening organ dysfunction caused by a dysregulated host response to infection. "For instance, the inhibition of the NF-kB/NLRP3 inflammasome signaling pathway by Maf1 could lead to attenuation of sepsis-associated encephalopathy." (PMID 35508474, 2022). "In the top ten genes with differential expression, we observed that the expression level of MAF1 was significantly reduced in sepsis rats when compared with control rats." (PMID 39833662, 2025). "In summary, this suggests that MAF1 and CUL2 expression were dysregulated during BBB injury in sepsis." (PMID 39833662, 2025). "However, while various mechanisms involving the AKT/FOXO1/MAF1 regulatory axis have been studied in cancer, they have not been studied in sepsis." (PMID 39833662, 2025).
ischemic stroke (3 papers, 2024 to 2025). A stroke disorder caused by obstruction of blood flow to the brain, due to thrombotic (local blood clot formation) or embolic (due to a blood clot or other material traveling from another site) event. "More work is needed to clarify the role of MAF1 and the underlying mechanisms in ischaemic stroke conditions." (PMID 39363536, 2024). "Further, consistent with findings that AD and VaD often co-exist, our AD TWAS identified genes that were associated with lacunar and ischemic strokes, as well as cerebral small vessel disease in other studies, including SLC39A13, RAPSN, MAF1, and MME." (PMID 40141087, 2025). "In a mouse in vivo stroke model, MAF1 was investigated in peri-infarct neurons during spontaneous recovery after ischaemic stroke." (PMID 39363536, 2024). "Further studies are warranted to delineate a detailed MAF1-mediated mechanism in the acute phase of ischaemic stroke in appropriate animal models." (PMID 39363536, 2024). "Collectively, these results demonstrate that MAF1 acts as an intrinsic suppressor against spontaneous neural repair and functional recovery after ischaemic stroke." (PMID 39363536, 2024). "They further suggest that MAF1 could be a potential therapeutic target for enhancing functional recovery after ischaemic stroke and other CNS injuries." (PMID 39363536, 2024). "Given that ischaemic stroke could induce DNA damage through oxidative stress, MAF1 knockout/knockdown might exacerbate oxidative damage in neurons by enhancing lipid peroxidation, necessitating investigation into potential alterations in Pol III transcription in this context." (PMID 39363536, 2024). "To date, robust data are still lacking on the role of MAF1 in ischaemic stroke." (PMID 39363536, 2024).